RNU6-976P (RNA, U6 small nuclear 976, pseudogene)
Gene: Small nuclear RNA gene on chromosome 14 (84,739,942 to 84,740,052, forward strand). Ensembl gene ENSG00000251895.
Homologues: Orthologues: chimpanzee U6 (98% identical). Paralogues in human: RNU6-1179P (68% identical), RNU6-429P (68% identical), RNU6-1205P (68% identical), RNU6-12P (68% identical), RNU6-13P (68% identical), RNU6-21P (68% identical), RNU6-235P (68% identical), RNU6-32P (68% identical), RNU6-331P (68% identical), RNU6-428P (68% identical), RNU6-463P (68% identical), RNU6-468P (68% identical), and 1281 more.